DNASE1 (deoxyribonuclease 1)
Diseases named in the same sentence as DNASE1 in open-access papers (continued):
Sharing a sentence is not in itself a finding about the gene and the disease.
cholestasis (2 papers, 2020 to 2025). Impairment of the bile flow caused by obstruction within the liver, or outside the liver in the bile duct system. "Deficiency of DNAse-1 (DNASE1), a cytoplasmic endonuclease degrading dsDNA, and lysosomal DNAse-2 (DNASE2) deficiency were reported in early-onset SLE patients who may exhibit “atypical” clinical features, such as neonatal pancytopenia, polyarthritis and cholestasis [57▪▪,58]." (PMID 39660463, 2025).
complement deficiencies (2 papers, 2016 to 2021). "With the exception of DNase1, DNase1L3, PRKCD deficiencies and complement deficiencies (for which no information on IFN expression is available), an increase in type I IFN activity was documented in the most part of affected patients." (PMID 27260006, 2016).
deep vein thrombosis (2 papers, 2021). "Similar results are captured when DNase1 is instead infused in deep vein thrombosis (DVT)-induced mice, showing a significant reduction in the mice that developed DVT after induction." (PMID 34944683, 2021).
kidney damage (2 papers, 2023). "In addition, the blood urea nitrogen (BUN) content was examined in aging Dnase1-/-, Dnase1-/- x Siglecg-/-, Dnase1l3-/- and Dnase1l3-/- x Siglecg-/- mice, Siglecg-/- mice and wt mice to examine the consequences of kidney damage." (PMID 36969253, 2023).
ovarian carcinoma (2 papers, 2013 to 2022). A malignant neoplasm originating from the surface ovarian epithelium. "The anti-EGFRvIII and anti-EGFR antibody guided vectors delivered the DNA constructs for DNase1, DNase1L3, DNase2, DFFB into the nuclei of the human EGFRvIII and EGFR over-expressing ovarian cancer cells from ascites and cultures." (PMID 24587967, 2013). "Furthermore, correlation analysis between 182 DEGs and MEX3A was applied using TCGA ovarian cancer data to obtain 7 DEGs (CSNKE1, OBSL1, DNASE1, ZNF711, TIMELESS, SAMD11, and BCL9) that were positively associated with MEX3A expression (Spearman’s correlation≥0.3)." (PMID 35715407, 2022).
varicocele (2 papers, 2020). A condition characterized by the dilated tortuous veins of the spermatic cord with a marked left-sided predominance. "Specifically, they found that levels of DNase1 were lower in adolescents with varicocele and normal sperm parameters and lowest in adolescents with varicocele and abnormal sperm parameters compared to healthy adolescents without varicocele." (PMID 33266209, 2020).
atherosclerosis (1 paper, 2025). A disease characterized by the build-up of fatty material and calcium deposition in the arterial wall resulting in partial or complete occlusion of the arterial lumen.
bronchiectasis (1 paper, 2022). Segmental, irreversible dilation of the bronchial tree resulting in the accumulation of secretions which leads to obstruction. "However, it should be noted that DNAse-1—despite its apparent benefits in accelerating the breakdown of coronary and cerebral thrombi—has in cases been harmful to bronchiectasis patients in one clinical trial." (PMID 36082273, 2022).
Crohn disease (1 paper, 2012). A gastrointestinal disorder characterized by chronic inflammation involving all layers of the intestinal wall, noncaseating granulomas affecting the intestinal wall and regional lymph nodes, and transmural fibrosis. "DNase1 has been implicated in a number of immune disorders and is an excellent candidate gene for Crohn's disease (CD)." (PMID 22701800, 2012).
end-stage renal disease (1 paper, 2010). "Dnase1 was diffusely expressed within the kidney in normal and mildly affected kidneys, whereas upon progression towards end-stage renal disease, Dnase1 was down-regulated in all renal compartments." (PMID 20856893, 2010).
glomerulosclerosis (1 paper, 2023). A hardening of the kidney glomerulus caused by scarring of the blood vessels. "However, both Dnase1-/- x Siglecg-/- and Dnase1l3-/- x Siglecg-/- mice revealed a significantly increased mean glomerulosclerosis index compared to Dnase1-/- and Dnase1l3-/- single knockout mice." (PMID 36969253, 2023).
hidradenitis suppurativa (1 paper, 2023). A chronic suppurative and cicatricial disease of the apocrine glands occurring chiefly in the axillae in women and in the groin and anal regions in men. "Similarly, combined deficiency in DNase1 and DNase1L3 due to neutralizing auto-antibodies, impairs NET clearance and underlies the inflammatory skin disorder hidradenitis suppurativa (acne inversa, 49)." (PMID 37287977, 2023).
hyperphosphatemia (1 paper, 2021). Abnormally high level of phosphate in the blood. "We showed that wild type mice on low phosphate diet and Fgf23−/− mice with hyperphosphatemia have increased renal Dnase1 mRNA expression while in Hyp mice with FGF23 excess and hypophosphatemia, Dnase1 mRNA expression is decreased." (PMID 33731726, 2021). "Adaptation to low and high phosphate diet were similar in Dnase1−/− and Dnase1+/+ mice, and loss of Dnase1 gene expression did not rescue hyperphosphatemia in Fgf23−/− mice." (PMID 33731726, 2021).
kidney cancer (1 paper, 2024). Primary or metastatic malignant neoplasm involving the kidney. "The imbalance in DNASE1 levels may affect the immune response in kidney cancer patients, as DNASE1 is involved in the clearance of apoptotic cells and immunological modulation by degrading extracellular DNA." (PMID 38618458, 2024). "The downregulation of DNASE1 in kidney carcinoma suggests a role in disease development." (PMID 38618458, 2024). "Therefore, DNASE1 dysregulation in kidney cancer may impede the body's ability to properly clear apoptotic cells and control immunological responses, resulting in a compromised immune system and potentially accelerating tumor development and spread." (PMID 38618458, 2024).
lupus-like syndrome (1 paper, 2006). "Of note, mice lacking DNase I (Dnase1-/-) have been shown to develop a spontaneous lupus-like syndrome." (PMID 16606442, 2006).
Miscarriage (1 paper, 2020). A pregnancy that ends at a stage in which the fetus is incapable of surviving on its own, defined as the spontaneous loss of a fetus before the 22th week of pregnancy. "Measurement results of DNASE1 levels showed significantly higher levels of DNASE1 in samples of women who have had a miscarriage in relation to those of the control group participants." (PMID 32753622, 2020).
Obesity (1 paper, 2020). Accumulation of substantial excess body fat. "This absence of therapeutic potential of DNASE1 may be due to soluble mediators present in obese mice that block DNASE1 function and/or to its inability to clear all sources of pathogenic DNA that accumulate during obesity." (PMID 33574823, 2020). "Indeed, DNASE1 is only capable of digesting “naked” DNA in the extracellular space, so exploring the role of other circulatory DNASES in the regulation of obesity-mediated pathogenesis is essential." (PMID 33574823, 2020).
pancreatic cancer (1 paper, 2020). "In pancreatic cancer, neutrophil extracellular traps (NETs) produced in response to pancreatic cancer metastases drive CAF formation in liver micrometastases, and treatment with DNase1 can significantly reduce CAF formation and metastasis growth in these models." (PMID 33370234, 2020).
Respiratory distress (1 paper, 2021). Respiratory distress is objectively observable as the physical or emotional consequences from the experience of dyspnea. "In the later phase, IL-6 levels are similar in severe and moderate illness, but NETosis-complement-coagulation leads to immunothrombosis, compounded by reduced clearance of the NETs (due to decreased levels of DNASE1), ultimately leading to acute respiratory distress in the severe cases." (PMID 34775962, 2021).
skin cutaneous melanoma (1 paper, 2024). "We also found that the expression of DNASE1 in skin cutaneous melanoma (SKCM) metastasis tissues was higher than that in SKCM tumor tissues, but there were no available data for comparing either SKCM tumor or metastasis tissues to normal tissues as of 2/11/2024." (PMID 38618458, 2024).
stomach adenocarcinoma (1 paper, 2024). "We also found that the missense mutation for DNASE1 was dominant and position A113V had the most mutations across 10,953 samples for UCEC (mutation samples = 9,686) and stomach adenocarcinoma (STAD, mutation samples = 1,144)." (PMID 38618458, 2024).
thyroid carcinoma (1 paper, 2024). "However, DNASE1 expression was significantly downregulated in three cancers: KIRC, KIRP, and THCA (thyroid carcinoma) compared to normal samples." (PMID 38618458, 2024).
tumor (32 papers, 1990 to 2026). "DNASE1 encodes Deoxyribonuclease1, which may be involved in clearance of cell-free DNA that serves as circulating tumor marker as well as playing a role in SLE pathogenesis." (PMID 35817785, 2022). "DNASE1 expression was found to be higher in tumor cells of hepatocellular carcinoma than in normal liver tissues, indicating its potential role in liver cancer." (PMID 38618458, 2024). "The degradation of extracellular DNA by DNASE1 produced by macrophages is expected to have significant implications for tumor growth and metastasis." (PMID 38618458, 2024). "We utilized the TIMER, GEPIA, and UALCAN datasets to explore the expression pattern of DNASE1 across various malignancies, aiming to determine significant differences in DNASE1 expression between normal and tumor samples." (PMID 38618458, 2024). "For example, DNASE1L3 (also named DNase1) is a DNA-degrading enzyme expressed at low levels in high-level glycolytic tumour cells." (PMID 37108242, 2023). "Staining of GC tissue derived from a subcutaneous tumor model in nude mice showed that ANGPT2 expression in DNAse-1-treated mice was significantly lower than in the control group." (PMID 36172371, 2022). "Studies have found a link between macrophages and DNASE1 in tumor cells." (PMID 38618458, 2024). "We investigated the correlation between DNASE1 and the prognosis of patients with KIRC and KIRP using the TIMER database while adding different clinical parameters for the Cox proportional hazard model: tumor purity, age, sex, race, and stage." (PMID 38618458, 2024). "In murine subcutaneous tumor tissues, ANGPT2 expression of DNAse-1-treated mice was significantly decreased, which proved that inhibition of NETs could significantly reduce ANGPT2 expression." (PMID 36172371, 2022).
cancer (24 papers, 2016 to 2025). A tumor composed of atypical neoplastic, often pleomorphic cells that invade other tissues. "We found a significant downregulation of DNASE1 expression in KIRC and KIRP compared to that in normal tissues, establishing the potential use of DNASE1 as a diagnostic biomarker in these cancers." (PMID 38618458, 2024). "Despite this, the use of DNASE1 as a diagnostic or prognostic biomarker in cancer remains unique, as does its relationship with other immune cells such as macrophages, CD8+ T cells, dendritic cells, and neutrophils." (PMID 38618458, 2024). "DNASE1 has also been linked to other immunological illnesses, including Crohn's disease, and proposed as a possible biomarker for cancer detection." (PMID 38618458, 2024). "We also used UALCAN to investigate the association between DNASE1 expression and clinicopathological parameters, including age, sex, race, individual cancer stage, and weight, focusing on two cancers: KIRC and KIRP." (PMID 38618458, 2024). "Furthermore, transcriptome analysis has highlighted the potential of genetic variations in DNASE1 as diagnostic and prognostic biomarkers for cancer." (PMID 38618458, 2024). "Additionally, we identified an association between DNASE1 genetic alterations and poor prognosis in 32 cancers using TCGA datasets obtained from the cBioPortal database." (PMID 38618458, 2024). "Reports have revealed that DNASE1 treatment results in decreased metastasis and cancer development in the lungs and liver." (PMID 38618458, 2024). "Exploring DNASE1 expression in various cancers is important for the potential identification of its use in the early detection of cancer and the evaluation of clinical outcomes of patients." (PMID 38618458, 2024). "DNASE1 expression was assessed using the UALCAN database to validate its expression in the 17 cancer samples collected from the TIMER database." (PMID 38618458, 2024). "Next, we established the relationship between DNASE1 expression and the survival outcomes of cancer patients using TIMER, UALCAN, and the Kaplan-Meier plotter." (PMID 38618458, 2024). "Our findings establish a starting point for exploring the correlation between DNASE1 expression and immune cell abundance in various cancers." (PMID 38618458, 2024). "The present study conducted a comprehensive analysis of deoxyribonuclease 1 (DNASE1) across various cancers using the TIMER." (PMID 38618458, 2024). "We found that the expression level of DNASE1 in normal samples was significantly upregulated in terms of age, sex, race, and cancer stage compared to that in KIRC and KIRP." (PMID 38618458, 2024). "For cancer‐upregulated genes with increased H3K4me3 levels, we observed a relatively higher distribution of fragments in the 50 to 160 bp range, along with a greater prevalence of cancer‐enriched motifs, DNase1 origin motifs and non‐DNase C‐end motifs." (PMID 39909829, 2025). "These genes exhibited a substantially higher proportion of short fragments, DNase1 origin motifs and cancer‐specific motifs compared with downregulated genes, suggesting that they undergo stronger digestion and are closely associated with cancer‐related DNase activities." (PMID 39909829, 2025). "We analyzed genetic variation in DNASE1 across various cancers using the cBioPortal platform." (PMID 38618458, 2024). "Cancer cells treated with recombinant DNases, including DNASE1, initiate programmed cell death." (PMID 38618458, 2024). "In summary, DNASE1 expression was downregulated in two cancers, namely, KIRC and KIRP." (PMID 38618458, 2024). "We provide a more in-depth analysis of DNASE1 expression across various cancers to understand its role and how it affects cancer progression, which provides insight for future investigations, particularly in early cancer detection and the identification of genetic alterations in DNASE1 in patients." (PMID 38618458, 2024).
cancer (continued). "There has been ongoing research on the correlation between DNASE1 and cancer; however, its mechanism of action remains unclear." (PMID 38618458, 2024). "Sixty-nine of the 125 cell types profiled by ENCODE have a DNase1 hypersensitive site (DHS1 site) at the BC041455 promoter, indicating diverse and complex regulation of this lncRNA in numerous human tissue types, and in primary (non-cancer) cells." (PMID 28003470, 2016). "Finally, public datasets were used to validate DNASE1 expression in various types of cancer." (PMID 38618458, 2024). "According to the individual cancer stages of patients with KIRC, DNASE1 was expressed lower in stage 1 (p = 1.64e-12), stage 2 (p = 2.14e-05), stage 3 (p = 2e-15), and stage 4 (p = 2e-15) than in normal tissues." (PMID 38618458, 2024). "Based on the individual cancer stages of KIRP patients, DNASE1 expression was lower in stage 1 (p = 1.93e-07), stage 2 (p = 1.75e-07), stage 3 (p = 1.61e-07), stage 4 (p = 1.98e-07) in KIRP patients than in normal tissues." (PMID 38618458, 2024). "It has been observed that a number of NRGs, including DNASE1, HMGB1 and PIK3CA, undergo gains in SCNV across a variety of cancer types, which was consistent with previous studies." (PMID 37408763, 2023). "Furthermore, we included two cancers (KIRC and KIRP) that were agreed between the three databases (UALCAN, TIMER, GEPIA) in terms of DNASE1 expression for further analysis." (PMID 38618458, 2024). "As a result of SCNV of NRGs in pan-cancer, we found SCNV gain in DNASE1, HMGB1 and PIK3CA." (PMID 37408763, 2023).
infection (7 papers, 2020 to 2024). The state of being infected such as from the introduction of a foreign agent such as serum, vaccine, antigenic substance or organism. "However, infection with Ad:XPO6 or Ad:mDIA-CT significantly reduced basal nuclear actin monomer levels and, importantly, completely reversed the forskolin induced increase in nuclear actin monomer levels, detected by DNAse1-Alexa Fluor-594 staining." (PMID 32119877, 2020).
renal disease (3 papers, 2006 to 2014). "Recent evidence points to an imbalance between NET formation and NET clearance in SLE and decreased NET degradation has been associated with complement activation and correlated with a subset of SLE patients with renal disease and attended by DNase1 inhibitors and anti-NET antibodies." (PMID 24804269, 2014). "Furthermore, the lack of a consistent correlation between serum and renal Dnase1 activity suggests that these reflect separate processes; the latter possibly confined to the kidney and related to the development of particularly unfavorable patterns of progression of the renal disease." (PMID 20856893, 2010).
immune disorders (2 papers, 2012 to 2021). "DNase1 is known to be involved in a number of immune disorders, but research into its role in CD has been rare." (PMID 22701800, 2012).
DNASE1 also shares sentences with these, for which no sentence is quoted: asthma (6 papers); breast cancer (6); lung disease (6); male infertility (4); colitis (3); hepatoma (3); lung carcinoma (3); melanoma (3); myocardial infarction (3); Venous thrombosis (3); acute kidney injury (2); colon carcinoma (2); dementia (2); inflammation (2); Lewis lung carcinoma (2); Renal failure (2); respiratory disease (2); thrombotic microangiopathies (2); vasculitis (2); viral infections (2); acne vulgaris (1); acute endometritis (1); acute lung injury (1); acute myocardial infarction (1); alopecia (1); bladder urothelial carcinoma (1); brain injury (1); cardiovascular disease (1); Cerebral ischemia (1); coagulopathies (1).
A further 54 diseases each share a sentence with DNASE1 in 1 paper.